S100A12 (S100 calcium binding protein A12)
Diseases named in the same sentence as S100A12 in open-access papers (continued):
Sharing a sentence is not in itself a finding about the gene and the disease.
atherosclerosis (continued). "Studies suggested that S100A12 could promote the occurrence and development of atherosclerosis by inducing the production of inflammatory factors." (PMID 36743388, 2023). "S100A12 play an important role in the development of atherosclerosis." (PMID 35224064, 2022). "Implications of S100A10 and S100A12 in atherosclerosis could entail differences in their expression in LEAD and CVD groups, however acetylic acid medication could also be causative for obtained results." (PMID 33801150, 2021). "S100A12 is involved in the pathogenesis of atherosclerosis through the S100A12-CD36 axis." (PMID 34804124, 2021). "Consequently, dysregulation in S100A12 secretion is found in many pathological situations like atherosclerosis, diabetes, chronic inflammatory disorders, and cancer." (PMID 27734162, 2017). "In atherosclerosis, S100A12 is expressed in macrophages and in vascular SMC, and may augment calcification." (PMID 23638054, 2013). "These include a negative association between sRAGE levels and coronary artery disease in non-diabetic men, prediction of unstable plaque by S100A8/A9 levels in acute coronary syndromes, and of accelerated atherosclerosis by high levels of S100A12 in hemodialysis patients." (PMID 19284577, 2009). "Thus, the interaction of S100A12 with RAGE may be involved in diverse processes such as inflammatory-induced atherosclerosis, defense against infection, and tumorigenesis." (PMID 23324110, 2013). "One study evaluated S100A12, a mediator of inflammatory response with RAGE receptor that appears to have increased levels in patients with atherosclerosis and recent symptoms of stroke." (PMID 37511304, 2023). "S100A12 and the RAGE axis are emerging pathways linking inflammation to atherosclerosis and vascular calcification as shown by enhanced vascular calcification in S100A12 transgenic mice." (PMID 30467547, 2018). "This distinguishes CD36 from other scavenger receptors, e.g., those of class A. Additionally, S100A12 and CD36 are expressed in similar cell types, and more interestingly, the dysregulation of S100A12 and CD36 is related to similar pathological outcomes like atherosclerosis." (PMID 27734162, 2017). "Recent data show that EN-RAGE (also called S100A12) contributes to inflammation and atherosclerosis and an early blockade of RAGE by statins may prevent inflammation in atherosclerosis." (PMID 23844967, 2013). "S100A12 is connected with NAFLD-related diseases (including obesity, type 2 diabetes, and inflammation) and may participate in the development of atherosclerosis by mediating the pathophysiological processes of vascular inflammation, calcification, and oxidative stress." (PMID 37090698, 2023).
inflammatory bowel disease (24 papers, 2010 to 2025). A spectrum of small and large bowel inflammatory diseases of unknown etiology. "In conclusion, we report that elevated levels of S100A12 are associated with gastroenteritis, necrotizing enterocolitis, gastritis, gastric cancer, Crohn's disease, irritable bowel syndrome, inflammatory bowel disease, and digestive tract cancers." (PMID 32184815, 2020). "Results suggest that S100A12 is implicated in gastroenteritis, necrotizing enterocolitis, gastritis, gastric cancer, Crohn's disease, irritable bowel syndrome, inflammatory bowel disease, and digestive tract cancers." (PMID 32184815, 2020). "In a number of gastrointestinal inflammatory diseases, such as necrotizing enteritis, inflammatory bowel disease, Crohn’s disease, irritable bowel syndrome, S100A12 levels are significantly elevated in affected tissues." (PMID 39825377, 2025). "In this study, we aimed to evaluate the use of serum pro-GN, PTX3 and S100A12 measurements in the differential diagnosis of inflammatory bowel disease." (PMID 37892129, 2023). "As for CP, S100A12 has also been shown to be increased in dogs with chronic inflammatory enteropathy, and has been used in humans to separate patients with inflammatory bowel disease from those with irritable bowel disease." (PMID 36230259, 2022). "Calprotectin, S100A12, and lactoferrin have generally been well described as fecal biomarkers in inflammatory bowel disease (IBD)." (PMID 28522897, 2017). "S100A12, a calcium-binding proinflammatory protein secreted by granulocytes, has been associated with different diseases of inflammatory origin, including inflammatory bowel disease (IBD)." (PMID 20946669, 2010). "To achieve this, we referred to our previous research, conducted in the Department of Clinical Chemistry and Laboratory Diagnostics, in which we assessed serum pro-GN, PTX3 and S100A12 concentrations in another type of inflammatory bowel disease—ulcerative colitis (UC)." (PMID 37892129, 2023). "In patients with Inflammatory Bowel Disease (IBD), in whom the incidence of sarcopenia is 42%, sarcopenia is associated with altered GM and increased levels of the gut inflammatory markers fecal calprotectin, lactoferrin and S100A12." (PMID 37752426, 2023). "We also assessed for any possible association of intestinal mucosal S100A12 concentrations and MPO activities with histopathological findings, canine inflammatory bowel disease activity index (CIBDAI) scores, clinical outcome, or hypoalbuminemia in dogs with CE." (PMID 29618371, 2018). "Also, serum levels of S100A8/S100A9 showed their utility in monitoring the presence of inflammation in patients with Crohn’s disease or ulcerative colitis, and S100A12 concentrations in the serum of patients with inflammatory bowel disease are correlated with disease activity." (PMID 37627347, 2023). "In addition, S100A12 has been measured in human saliva in inflammatory bowel disease." (PMID 37627347, 2023). "The S100A12 protein is a ligand for the pattern recognition receptor RAGE (receptor for advanced glycation end products) and activates the nuclear factor kappa B (NF-kB) pathway, a mechanism linked to the pathogenesis of autoimmune disorders such as inflammatory bowel disease (IBD) in humans." (PMID 29665827, 2018). "Previous data suggest that fecal S100A12 has clinical utility as a biomarker of chronic gastrointestinal inflammation (idiopathic inflammatory bowel disease) in both people and dogs, but the effect of gastrointestinal pathogens on fecal S100A12 concentrations is largely unknown." (PMID 29665827, 2018). "There are a number of studies examining serum S100A12 concentrations in patients with inflammatory bowel disease (IBD)." (PMID 22811950, 2012). "Intestinal mucosal S100A12 and myeloperoxidase (MPO) are inflammatory biomarkers in humans with inflammatory bowel disease (IBD)." (PMID 29618371, 2018).
inflammatory bowel disease (continued). "The findings for some of the stool proteins appear consistent with expectations based on the literature, such as the increase in fecal S100A12 in NEC infants and the elevation of mucosal DEFA5, Serpin B1 and peroxiredoxin-1 in NEC infants and/or patients with inflammatory bowel disease." (PMID 36232903, 2022).
Crohn disease (17 papers, 2010 to 2025). A gastrointestinal disorder characterized by chronic inflammation involving all layers of the intestinal wall, noncaseating granulomas affecting the intestinal wall and regional lymph nodes, and transmural fibrosis. "In clinical practice, S100A12 is anticipated to serve as a diagnostic biomarker and aid in assessing disease activity in individuals with Crohn’s disease." (PMID 40540498, 2025). "In this study, we aimed to evaluate the utility of pro-GN, PTX3 and S100A12 as diagnostic markers of Crohn’s disease." (PMID 37892129, 2023). "S100A12 serum levels were determined in 64 patients with ulcerative colitis (UC), 64 with Crohn's disease (CD) and 73 with IBS, by means of an enzyme-linked immunosorbent assay." (PMID 20946669, 2010). "Considering the role of the analyzed proteins in the pathogenic process and the obtained results, the measurements of serum PTX3 and S100A12 may be used during the diagnostic process for Crohn’s disease." (PMID 37892129, 2023). "In this study, we also assessed the concentration of pentraxin 3 and S100A12, which are proteins related to the innate immune response and are engaged in the development of inflammation, being an integral part of the pathogenic process during Crohn’s disease." (PMID 37892129, 2023). "The conducted statistical analyses revealed a significant difference in the serum profiles of pro-GN, PTX3 and S100A12 between patients with Crohn’s disease and healthy individuals, indicating the diagnostic usefulness of all the analyzed biomarkers in this disease." (PMID 37892129, 2023). "A biochemical study suggested that S100A12 was one of the important genes in the co-occurrence of Crohn’s disease and PAD, and that neutrophil infiltration-mediated inflammation and immune modulation were important pathological processes involved." (PMID 40269701, 2025). "Among patients with Crohn’s disease and ulcerative colitis, another difference was noted in the case of S100A12, the concentration of which was increased in the serum of CD patients compared to UC." (PMID 37892129, 2023). "Specifically, the concentration of PTX3 was increased in the group of patients with ulcerative colitis, while the S100A12 level was elevated in patients with Crohn’s disease." (PMID 37892129, 2023). "Regarding the crucial relationship between the analyzed biomarkers and the pathogenic process during Crohn’s disease, we also assessed the usefulness of serum pro-GN, PTX3 and S100A12 measurements in evaluating disease activity." (PMID 37892129, 2023). "For instance, serum S100A12 levels have been associated with response to anti-TNF therapy in patients with juvenile idiopathic arthritis and Crohn’s disease." (PMID 36555597, 2022). "Regarding the contribution of proguanylin to intestinal barrier integrity and pentraxin 3 along with S100A12 to innate immunity, these mentioned biomarkers may be useful in the diagnosis of Crohn’s disease." (PMID 37892129, 2023). "The results obtained from this investigation suggest that measurements of pro-GN, PTX3 and S100A12 could prove beneficial in the diagnosis of Crohn’s disease." (PMID 37892129, 2023). "Another neutrophil-derived inflammatory product, S100A12, may similarly contribute to the initiation and progression of Crohn’s disease." (PMID 37892129, 2023). "A comparison of CF children to healthy controls and children with Crohn’s disease showed that CF intestinal inflammation is distinct from that seen in patients with Crohn’s disease and is characterized by elevated calprotectin but normal levels of the biomarkers S100A12 and osteoprotegerin." (PMID 26549988, 2015). "Therefore, the hypothesis of our study is that pro-GN, PTX3 and S100A12 measurements in the serum of patients with Crohn’s disease are useful in diagnosing and monitoring the activity of the disease." (PMID 37892129, 2023).
Crohn disease (continued). "Other potential biomarkers of Crohn’s disease analyzed in this study are pentraxin 3 (PTX3) and s100A12 protein, both of whose function is related to the immune response." (PMID 37892129, 2023). "Patients with Crohn’s disease presented a decreased concentration of PTX3 (p < 0.005), while the level of S100A12 (p < 0.05) was increased compared to the subjects with ulcerative colitis before treatment." (PMID 37892129, 2023). "However, regarding the crucial differences in PTX3 and S100A12 serum profiles in patients with Crohn’s disease and ulcerative colitis, together with its varied synthesis and release during the diseases, our study indicate that these biomarkers might be useful in the differential diagnosis of IBD." (PMID 37892129, 2023). "This bioinformatic study elucidates S100A8, S100A9, S100A12 and CXCR2 as hub genes for the co-occurrence of Crohn’s disease and peripheral artery disease." (PMID 35795659, 2022). "S100A12 also exists in a dimer or hexamer form, and Ca2+-bound forms of S100A12 are reported to bind directly to soluble tumor necrosis factor (TNF) and affect the efficacy of anti-TNF therapy in patients with juvenile idiopathic arthritis and Crohn’s disease." (PMID 38256103, 2024). "In Crohn’s disease, enhanced expression of both RAGE and S100A12 has been observed." (PMID 37892129, 2023). "Moreover, as the median CRP concentration in the blood of patients with Crohn’s disease was increased compared to the reference values, we estimated the correlation between the level of this inflammatory marker and serum profiles of pro-GN, PTX3 and S100A12." (PMID 37892129, 2023). "Meanwhile, the level of S100A12 also decreased, however not statistically significantly, indicating the predominance of pro-GN and PTX3 assessments in evaluating the beneficial effect of corticosteroid therapy in the course of Crohn’s disease." (PMID 37892129, 2023).
coronary artery disease (16 papers, 2009 to 2023). "Participants in the highest tertile of S100A12 levels had a 2.6-fold higher risk of developing coronary artery disease compared with participants in the lowest tertile." (PMID 30467547, 2018). "S100A12 remained significantly associated with coronary artery disease when adjusted for age and sex." (PMID 30467547, 2018). "The hub gene S100A12 has been shown to have a regulatory role in carotid plaque instability and the occurrence of major cardiovascular events in patients with stable coronary artery disease." (PMID 36034287, 2022). "Previous studies have reported that S100A12 was an important inflammatory marker in coronary heart disease, therefore, TLR4 and TREM1 were further studied." (PMID 34221733, 2021). "Higher expression of S100A12 was identified as a biomarker of coronary artery disease, aortic calcification, increased plaque vulnerability and as predictor of cardiovascular events." (PMID 33801150, 2021). "Taken together, the expression of sRAGE and S100A12 in patients with coronary artery disease is controverting." (PMID 31275446, 2019). "The expression of sRAGE and S100A12 in patients with coronary artery disease from different studies was inconsistent." (PMID 31275446, 2019). "The vascular pathology observed in S100A12/ApoE null mice consisting of intimal calcification, large necrotic core, and breakdown of elastic fibers models features that are seen in human coronary artery disease." (PMID 30467547, 2018). "Protein S100-A12 (EN-RAGE), the ligand for RAGE, has been associated with incident type 2 diabetes and risk of coronary heart disease." (PMID 29796748, 2018). "The increase of S100A12 protein level in blood, which is related to the fragility and rupture of atherosclerotic plaque, has been demonstrated to be a powerful predictor of the progression of stable coronary heart disease to acute coronary syndrome." (PMID 35722095, 2022). "Similarly, increased expression of S100A12 has been reported in PBMCs from patients with pre-mature coronary artery disease." (PMID 32082330, 2020). "In our study, the patients were divided into diabetic and nondiabetic subgroups, and the results showed that in different types of coronary heart disease patients, the plasma levels of sRAGE and S100A12 were all increased in patients with diabetes mellitus compared with nondiabetic patients." (PMID 31275446, 2019). "Using ROC curve to determine the predictive values of sRAGE and s100A12 on severe coronary heart disease, we found that sRAGE combined with S100A12 may be used as a predictor of severe coronary heart disease." (PMID 31275446, 2019). "In this study with 10 year follow up, baseline S100A12 serum concentrations had predictive value for development of coronary artery disease, acute myocardial infarction, and cardiovascular mortality in this population-based cohort study of 839 participants without coronary heart disease at baseline." (PMID 30467547, 2018). "sRAGE combined with S100A12 may be used as a predictor of severe coronary heart disease." (PMID 31275446, 2019). "An elevated S100A12 level in ESRD patients is correlated with CVD, such as ischemic heart disease, stroke, and peripheral vascular disease." (PMID 26914918, 2016). "Circulating S100A12 levels are not elevated in patients with stable coronary artery disease but are increased in those with acute coronary syndromes (ACS) and after percutaneous coronary intervention (PCI) due to acute release of S100A12 from macrophages after plaque rupture or mechanical injury." (PMID 34977174, 2021).
juvenile idiopathic arthritis (16 papers, 2012 to 2024). Juvenile idiopathic arthritis (JIA) is the term used to describe a group of inflammatory articular disorders of unknown cause that begin before the age of 16 and last over 6 weeks. "Five differentially expressed genes of interest were validated by qRT-PCR, among which S100A12 was observed to be elevated in the saliva of SAPHO patients and serum S100A12 is related to juvenile idiopathic arthritis-associated uveitis." (PMID 31395074, 2019). "This study aimed to investigate the propensity of S100A8/9 and S100A12 as predictive biomarkers of abatacept response in polyarticular-course juvenile idiopathic arthritis (pJIA)." (PMID 38918871, 2024). "The amount of S100A12 protein is also known to increase in cases of malignancies, obstructive sleep apnea, autoimmune diseases, systemic lupus erythematosus, juvenile arthritis, and FMF." (PMID 33576586, 2021). "ROC analysis evaluating S100A12 levels performed in a study that differentiated juvenile idiopathic arthritis patients with Kawasaki disease revealed an ROC curve of 0.97 (95% confidence interval, 0.89–1)." (PMID 33576586, 2021). "Because S100A12 is involved in many different diseases, such as Juvenile Rheumatoid Arthritis (JRA), asthma, Behçet's, Kawasaki disease, and IBD, it is natural that researchers would attempt to target this interaction pharmacologically." (PMID 32184815, 2020). "Notably, the reduction effect of canakinumab on the concentrations of IL-1RA, IL-6, IL-18 and S100A12 in our cohort had been confirmed recently in a systemic juvenile idiopathic arthritis cohort." (PMID 34640417, 2021). "Several studies have examined the patterns of serum S100A12 in juvenile idiopathic arthritis (JIA)." (PMID 22811950, 2012). "In another study, researcher aimed to evaluate whether a potential relationship might exist between S100A12, Toll-like receptor 4 (TLR4) and the disease activity of both FMF and juvenile idiopathic arthritis (JIA)." (PMID 39132307, 2024). "A recent study analyzed the relationship between serum S100A8/S100A9 and S100A12 and the maintenance of clinical inactive disease (CID) in patients with polyarticular forms of juvenile idiopathic arthritis (PF-JIA) while on anti-TNF- therapy and disease flare following withdrawal of treatment." (PMID 30828327, 2019).